SALL1 (spalt like transcription factor 1)
Description:
Transcriptional repressor involved in organogenesis. Plays an essential role in ureteric bud invasion during kidney development.
Synonyms: HSal1; Sal-1; ZNF794; HEL-S-89; TBS
Tractability: PROTAC: UniProt records ubiquitination sites on it.
Gene: Protein-coding gene on chromosome 16 (51,135,982 to 51,152,683, reverse strand). Ensembl gene ENSG00000103449.
Subcellular location: Nucleus
Subcellular location (Human Protein Atlas): Nucleoplasm; Cytosol; Nuclear speckles; Nucleoli
Pathways (Reactome):
Developmental Biology: Formation of the ureteric bud; POU5F1 (OCT4), SOX2, NANOG activate genes related to proliferation
Gene Ontology:
Molecular function: beta-catenin binding; protein binding; DNA-binding transcription factor activity, RNA polymerase II-specific
Biological process: adrenal gland development; embryonic digestive tract development; embryonic digit morphogenesis; gonad development; heart development; kidney development; limb development; mesenchymal to epithelial transition involved in metanephros morphogenesis; negative regulation of DNA-templated transcription; negative regulation of transcription by RNA polymerase II; olfactory bulb mitral cell layer development; pituitary gland development; positive regulation of DNA-templated transcription; positive regulation of transcription by RNA polymerase II; positive regulation of Wnt signaling pathway; branching involved in ureteric bud morphogenesis; inductive cell-cell signaling; kidney epithelium development; olfactory bulb interneuron differentiation; olfactory nerve development; regulation of transcription by RNA polymerase II; ureteric bud development; ureteric bud invasion; ventricular septum development; olfactory bulb development; and 2 more
Cellular component: chromocenter; cytoplasm; heterochromatin; nucleus; nucleoplasm
Genetic constraint (gnomAD): Loss-of-function variants: 10 observed, 74.54 expected, observed/expected ratio (o/e) 0.13, 90% interval 0.082 to 0.23. The upper end of that interval is the gene's LOEUF score, 0.23, which puts it in group 1 of 6, group 1 being the genes least tolerant of losing a copy. Missense variants: 1,520 observed, 1,767.5 expected, observed/expected ratio (o/e) 0.86, 90% interval 0.82 to 0.9. Synonymous variants: 688 observed, 717.97 expected, observed/expected ratio (o/e) 0.96, 90% interval 0.9 to 1.02.
Gene-disease validity (ClinGen):
ClinGen rates the evidence that SALL1 causes each of these diseases.
Townes-Brocks syndrome 1 (autosomal dominant): Definitive.
Homologues: Orthologues: chimpanzee SALL1 (99% identical), macaque SALL1 (98% identical), dog SALL1 (94% identical), pig SALL1 (93% identical), guinea pig SALL1 (92% identical), mouse Sall1 (90% identical), rat Sall1 (90% identical), tropical clawed frog sall1 (78% identical), zebrafish sall1a (68% identical), zebrafish sall1b (46% identical). Paralogues in human: SALL3 (51% identical), SALL4 (34% identical), SALL2 (22% identical), HIVEP1 (15% identical), HIVEP3 (14% identical), ZNF536 (13% identical), HIVEP2 (13% identical), BCL11B (11% identical), ZNF516 (11% identical), BCL11A (10% identical), RREB1 (10% identical), ZNF831 (9% identical), and 2 more.
Diseases named in the same sentence as SALL1 in open-access papers:
SALL1 is named in the same sentence as 139 diseases in open-access papers, as found by Europe PMC text mining. Sharing a sentence is not in itself a finding about the gene and the disease. The quoted sentences say what the papers report.
Townes-Brocks syndrome (36 papers, 2009 to 2025). Townes-Brocks syndrome (TBS) is a rare genetic disorder characterized by the triad of imperforate anus, dysplastic ears often associated with sensorineural and/or conductive hearing impairment, and thumb malformations. "Pathogenic SALL1 variants cause Townes-Brocks syndrome 1 (TBS1), which typically presents with imperforate anus, dysplastic ears, and digital anomalies." (PMID 40658219, 2025). "SALL1 is essential for kidney development, evidenced by its homozygous deletion in mice leading to severe defects in the kidney, while in humans, SALL1 mutation causes Townes-Brocks syndrome, featuring anomalies in the ear, anus, kidney, and heart." (PMID 39349437, 2024). "In Townes-Brocks syndrome, thumb deformity has been reported together with abnormal foot postures due to heterozygous pathogenic variants in SALL1." (PMID 39850168, 2024). "According to earlier studies, SALL1 heterozygous deletions can cause Townes-Brocks syndrome or at least a milder form of the condition." (PMID 38915054, 2024). "Previous studies have revealed that mutations in the SALL1 gene can disrupt normal development, resulting in the characteristic features of Townes-Brocks syndrome." (PMID 38915054, 2024). "In humans, mutations in SALL1 are associated with a congenital malformation syndrome that affects limbs, kidneys and ears (Townes Brocks syndrome, OMIM 107480)." (PMID 37519269, 2023). "Identification of new SALL1 mutations and study of the relation between SALL1 mutations and clinical features can facilitate diagnosis of Townes-Brocks syndrome." (PMID 37644569, 2023). "The correlation between genotypes and renal phenotypes in Townes-Brocks syndrome patients caused by SALL1 mutation were summarized." (PMID 37644569, 2023). "Although heterozygous variants of SALL1 cause Townes-Brocks syndrome, comprising of facial dysmorphism, limb defects, kidney and urinary tract abnormalities and anorectal malformation, isolated kidney and urinary tract abnormalities have also been reported." (PMID 34979951, 2022). "This is particularly interesting as autosomal dominantly inherited variants in SALL1 are known to cause Townes-Brocks syndrome (MIM# 107480), with genitourinary malformations being one of the syndromes features." (PMID 36238604, 2022). "Variants in SALL1 are associated with Townes-Brocks syndrome (OMIM #107480), an autosomal dominant disorder characterized by ARM, thumb anomalies, renal anomalies, cardiac anomalies, dysplastic ears, and hearing loss." (PMID 32656166, 2020). "For instance, a mutation in SALL1 is linked to the autosomal disease, called Townes-Brocks syndrome, while mutant forms of SALL2 are present in human ovarian carcinoma and a mutation in SALL4 leads to Okihiro syndrome (Duane-radial ray syndrome)." (PMID 32718932, 2020). "Mutations in SALL1 have been associated with Townes-Brocks syndrome, a condition associated with renal malformation, suggesting a role of SALL1 in genitourinary development." (PMID 32184442, 2020). "In humans, heterozygous mutations of SALL1 can lead to Townes-Brocks syndrome, an autosomal dominant developmental disorder that is characterized by kidney and heart anomalies together with other phenotypic abnormalities." (PMID 29484122, 2018). "The important role of SALL1, a homeotic gene and a transcription factor, in human development was recognized because heterozygous SALL1 mutations lead to Townes-Brocks syndrome." (PMID 29484122, 2018). "Mutations in SALL1 and a deletion at the GWAS signal have been associated with Townes-Brocks syndrome, a condition associated with kidney malformations." (PMID 30226466, 2018). "Defects in the human orthologue of this gene, SALL-1, are a cause of Townes-Brocks syndrome (TBS) (OMIM #107480) as well as branchio-oto-renal syndrome (BOR) (OMIM # #113650)." (PMID 24740420, 2014).
Townes-Brocks syndrome (continued). "In humans, SALL1 is mutated in patients with Townes-Brockes Syndrome (TBS), with features that include renal, limb, anal, and ear malformations." (PMID 20505821, 2010). "Townes-Brocks syndrome affecting limb, ear, kidney and heart development is caused by defects in the SALL1 gene." (PMID 20205715, 2010). "Therefore, we conclude that in our patient, a novel mutation in the SALL1 gene is a cause of Townes-Brocks syndrome, diagnosed in our patient." (PMID 40989825, 2025). "Additionally, targeted mutation analysis of the SALL1 gene identified 1 case of Townes-Brocks syndrome based on clinical suspicion." (PMID 41527628, 2025). "This loop explains the overlapping phenotypes of four syndromes: Duane-radial ray syndrome with SALL4 mutations (MIM 607323); Fanconi anemia (MIM 227650); Holt-Oram syndrome with TBX5 mutations (MIM142900); and Townes-Brocks syndrome with SALL1 mutations (MIM 107480)." (PMID 29651423, 2018). "Functional redundancy between Sall factors is likely to compensate for the heterozygous loss of Sall2 in the eye, particularly Sall1 which is expressed in the developing eye and can be associated with retinochoroidal coloboma in some cases of Townes-Brocks syndrome." (PMID 24412933, 2014). "This region includes SALL1, which causes Townes-Brocks syndrome." (PMID 20003547, 2009). "This list includes the SALL1 gene, which when mutated causes Townes-Brocks syndrome." (PMID 20003547, 2009). "Moreover, the marker genes that we found to specifically label Duo identity include SP5 and SALL1, the latter of which has been linked to Townes-Brocks syndrome with developmental malformation of multiple organs including the limb, kidney and gastrointestinal tract." (PMID 33406262, 2021). "SALL1 is a stem cell factor in kidney development, and is mutated in patients with Townes-Brocks syndrome (TBS), whose features include renal malformations." (PMID 19440552, 2009). "Molecular evaluation of this patient showed a deletion of 16q, which includes the SALL1 gene, which causes Townes-Brocks syndrome (TBS, MIM 107480)." (PMID 20003547, 2009). "We note that several of the highly correlated genes-SALL4 (Duane-Radial Ray Syndrome), PAX2 (Papillorenal syndrome), ACGT1 (Baraitser-Winter Syndrome 2), SALL1 (Townes-Brocks Syndrome 1) can also present with congenital renal anomalies." (PMID 40610405, 2025). "We note that several of the enriched genes-SALL4 (Duane-Radial Ray Syndrome), PAX2 (Papillorenal syndrome), ACGT1 (Baraitser-Winter Syndrome 2), SALL1 (Townes-Brocks Syndrome 1) can also present with congenital renal anomalies." (PMID 39606382, 2024). "Diagnosis of Townes-Brocks syndrome (TBS) involves a combination of clinical evaluation, imaging studies, and genetic testing to identify mutations in the SALL1 gene." (PMID 38915054, 2024). "Two cases each carried disease-causing variants in SALL1 and EYA1, both well-known autosomal dominant syndromic monogenic CAKUT genes (Townes-Brocks syndrome 1, MIM #107480; and branchiootorenal syndrome 1, MIM #113650)." (PMID 36922632, 2023). "Based on the pathogenic variant in SALL1 and the fact that ARM is a major clinical feature of Townes-Brocks syndrome, the patient was diagnosed with this syndrome." (PMID 32656166, 2020). "Mutations in SALL1 and SALL4 have been associated with Townes-Brocks syndrome and Okihiro syndrome, respectively, which are both autosomal dominant diseases that involve abnormalities in various organs, including the ears, limbs, heart, and kidneys." (PMID 23825698, 2013). "Through our studies on Townes-Brocks Syndrome (TBS), a rare disease linked to abnormal cilia formation in human fibroblasts, we uncovered the leucine-zipper protein LUZP1 as an interactor of truncated SALL1, a dominantly-acting protein causing the disease." (PMID 32553112, 2020).
Townes-Brocks syndrome (continued). "Townes-Brocks Syndrome (TBS1 [MIM: 107480]) is an autosomal dominant genetic disease, caused by mutations in a transcription factor called SALL1, characterized by the presence of imperforate anus, dysplastic ears, thumb malformations and often renal and heart impairment, among other symptoms." (PMID 32553112, 2020). "In retrospect, this child has a number of features that can be explained by the SALL1 deletion, although it is not clear if the microphthalmia is a rare feature of Townes-Brocks syndrome or caused by other mechanisms." (PMID 20003547, 2009). "After exclusion of BOR syndrome, we therefore proceeded with WES testing of patient and parents, which revealed a de novo pathogenic mutation in SALL1 gene, usually consistent with Townes-Brocks syndrome, however with absence of cardinal features, such as anorectal and limb malformations." (PMID 40989825, 2025). "Townes-Brocks syndrome (TBS, MIM#107480) is an autosomal dominant disorder linked to SALL1 alterations and characterized by a clinical triad (anorectal, thumb, and external-ear malformations), along with variable features." (PMID 40348827, 2025). "TBS is an autosomal dominant malformation syndrome caused by SALL1 mutations and approximately one in three patients have not family history with Townes-Brocks syndrome." (PMID 37644569, 2023). "In addition to the SALL1 gene, recent studies found that mutations in the Dishevelled Binding Antagonist Of Beta Catenin 1 (DACT1) gene located on chromosome 14q23 may also lead to TBS, which is called Townes-Brocks syndrome-2 (TBS2; 617466)." (PMID 33478437, 2021). "It is interesting to note that Townes-Brocks syndrome is the only LPAD syndrome in which PPD is commonly seen in the phenotype; and this is to be expected since SALL1 is the link between the two loops." (PMID 29651423, 2018). "The other phenotypes observed in Townes-Brocks syndrome are not apparent, because truncated Sall1 proteins produced in humans are likely to inhibit other Sall family proteins in a dominant-negative manner." (PMID 23825698, 2013).
breast carcinoma (15 papers, 2010 to 2026). "They further showed that high expression of SALL1 was associated with significantly increased relapse-free survival, overall survival, metastasis-free survival, and tumor-free survival of breast cancer patients." (PMID 29625565, 2018). "To further identify mechanism(s) responsible for the down-regulation of SALL1 gene in breast cancer, we explored the mutations and promoter methylation status of the SALL1 gene via The Catalogue of Somatic Mutations in Cancer (COSMIC) genome browser." (PMID 29625565, 2018). "(B) The COSMIC analysis shows the mutations and the promoter methylation status of SALL1 gene in breast cancer tissues." (PMID 29625565, 2018). "We next utilized SALL1 constructs with these two separation-of-function mutations to test its effects on senescence induction in breast cancer cells." (PMID 29625565, 2018). "Using both gain-of function and loss-of-function strategies, we showed that SALL1 expression in breast cancer cells inhibited tumor cell growth and proliferation, promoted cell cycle arrest, and induced cell senescence." (PMID 29625565, 2018). "Our current work further suggests a causative link between SALL1 gene regulation, NuRD complex function, and breast cancer pathogenesis." (PMID 29625565, 2018). "However, the molecular mechanism and causative role of SALL1 in the regulation of breast cancer development and tumorigenesis are not well understood." (PMID 29625565, 2018). "We identified that ATM-associated DNA damage is responsible for SALL1-mediated breast cancer cell senescence, by analyzing activation of ATM and its related targets, as well as using loss-of-function approaches with a specific pharmacological ATM inhibitor and shRNA." (PMID 29625565, 2018). "To further confirm the functional role of SALL1 in regulating breast cancer cell growth, we also utilized a loss-of-function strategy to knockdown SALL1 gene expression with lentivirus-based shRNA in breast cancer cell lines and then determined its effect on tumor growth and proliferation." (PMID 29625565, 2018). "In addition, SALL1 hyper-methylation has already been confirmed as the diagnostic biomarker for breast cancer and other epithelial cancers, especially for the colorectal cancer." (PMID 30233644, 2018). "To test this hypothesis, we first transfected a mutated SALL1 (mSALL1) encoding a protein in which the conserved 12-amino acid peptide motif that specifically binds to NuRD was deleted, into breast cancer cells and determined the capacity for senescence induction." (PMID 29625565, 2018). "On the other hand, SALL1, which is suppressed in breast cancer, was ubiquitously downregulated in tumors, while being steadily expressed in both stem cells and normal tissues." (PMID 35587924, 2022). "One SNP near SALL1, in relation to CRP, both overall and in the obesity strata, is associated with breast cancer risk." (PMID 33441805, 2021). "Our finding of the SALL1 SNP’s association with CRP at the GWA level and with breast cancer risk is supported by these previous biologic studies and further suggests the involvement of SALL1 in immune mechanisms of breast cancer tumorigenesis." (PMID 33441805, 2021). "SALL1 is bound to the NuRD complex in breast cancer; thus, it is likely that SALL1 and SALL4 share a similar repressive mechanism for PTEN regulation." (PMID 34944911, 2021). "SALL1/NuRD inhibited breast cancer cell growth, proliferation, and metastasis, and a phosphomimetic mutation of SALL1 impaired its tumor suppressor function." (PMID 34944911, 2021). "Altogether, studies suggest that in breast cancer, SALL1 and SALL4 are involved in migration, invasion, and EMT by regulating common targets such as E-cadherin and vimentin, but in an opposite manner." (PMID 34944911, 2021). "Consistent with its tumor suppressor role in breast cancer, SALL1 inhibited tumor growth, metastasis in the lung and liver, and promoted cell cycle arrest and senescence." (PMID 34944911, 2021).